RN7SKP91 (RN7SK pseudogene 91)
Gene: Miscellaneous RNA gene on chromosome 1 (30,843,823 to 30,844,110, forward strand). Ensembl gene ENSG00000222784.
Homologues: Orthologues: chimpanzee 7SK (93% identical), guinea pig 7SK (64% identical), mouse Gm55668 (62% identical). Paralogues in human: 7SK (80% identical), RN7SKP80 (77% identical), RN7SKP203 (77% identical), RN7SKP176 (76% identical), RN7SKP255 (76% identical), RN7SKP9 (76% identical), RN7SKP160 (76% identical), RN7SKP185 (75% identical), RN7SKP187 (75% identical), RN7SKP170 (75% identical), RN7SKP217 (75% identical), RN7SKP118 (75% identical), and 284 more.